PCSK9 (proprotein convertase subtilisin/kexin type 9)
Diseases named in the same sentence as PCSK9 in open-access papers (continued):
Sharing a sentence is not in itself a finding about the gene and the disease.
Myocardial fibrosis (3 papers, 2022 to 2026). "Cellular sequencing analysis of the two groups of mice reported that platelet‐associated Itga2b is a key mediator through which PCSK9 affects post‐AMI myocardial fibrosis." (PMID 41573336, 2026). "In the previous section, we demonstrated that PCSK9 promotes myocardial fibrosis via platelet activation; however, the underlying pathway and mechanism remain unclear." (PMID 41573336, 2026). "Our study is the first to suggest that PCSK9 promotes postinfarction myocardial fibrosis by increasing the level of platelet‐derived TGF‐β." (PMID 41573336, 2026). "This is the first study to propose that PCSK9 affects myocardial fibrosis through the interaction between platelets and cardiac fibroblasts." (PMID 41573336, 2026). "The degree of myocardial fibrosis was evaluated via Masson’s trichrome staining, which revealed that myocardial fibrosis was significantly reduced in PCSK9‐KO mice after AMI compared with that in the WT AMI group (fp < 0.0001)." (PMID 41573336, 2026). "In our study, we revealed that PCSK9 affects myocardial fibrosis after MI through platelet‐derived TGF‐β." (PMID 41573336, 2026). "A prior study has shown that another PCSK9 inhibitor, evolocumab, attenuated myocardial fibrosis in rats with ischemia reperfusion injury and HF, supporting the findings of our study." (PMID 40076547, 2025). "We found that PCSK9 deletion facilitates the repair of postinfarction myocardial fibrosis." (PMID 41573336, 2026). "PCSK9 promotes platelet activation, induces the secretion of platelet‐derived TGF‐β, and thereby accelerates myocardial fibrosis after MI." (PMID 41573336, 2026). "To investigate the role of PCSK9 in myocardial fibrosis after AMI, we constructed PCSK9 knockout (KO) mice." (PMID 41573336, 2026). "However, the role of PCSK9‐induced platelets in myocardial fibrosis remains unclear." (PMID 41573336, 2026). "In the present study, we demonstrated that PCSK9 promotes platelet activation and induces platelet‐derived TGF‐β secretion and promotes myocardial fibrosis after MI." (PMID 41573336, 2026).
myositis (3 papers, 2016 to 2025). "This study aims to describe the clinical characteristics of SAIMNM patients and evaluate the safety of PCSK9 inhibitors after myositis onset." (PMID 40249406, 2025). "After multiple statin failures due to side effects like myositis and discontinuation of ezetimibe for claimed gastrointestinal intolerance, she was prescribed a PCSK9 inhibitor." (PMID 41404258, 2025). "The interval between the onset of myositis and the initiation of PCSK9 inhibitors varied depending on the patient’s symptoms." (PMID 40249406, 2025). "In all cases, there was no relapse of myositis with PCSK9 inhibitors, except for one patient in Tinakou study, where active disease persisted, necessitating an escalation of immunosuppressant therapy." (PMID 40249406, 2025).
neural tube defect (3 papers, 2015 to 2023). A congenital defect characterized by failure of the neural tube to close completely; this results in the presence of openings in the brain or spinal cord. "Given the importance of PCSK9 in neuronal differentiation, low maternal PCSK9 serum levels are associated with fetal neural tube defects (NTDs)." (PMID 32595449, 2020). "In contrast, PCSK9 concentrations are lower in the plasma and amniotic fluid of pregnant female rats as well as in rat embryos with experimentally induced neural tube defects and the plasma of pregnant women with fetuses suffering from open neural tube defects." (PMID 37586604, 2023).
osteoporosis (3 papers, 2022 to 2024). A condition of reduced bone mass, with decreased cortical thickness and a decrease in the number and size of the trabeculae of cancellous bone (but normal chemical composition), resulting in increased fracture incidence. "By combining drug-targeted MR with mediation analysis, we explored the relationship between PCSK9 inhibitors and the risk of osteoporosis." (PMID 38789568, 2024). "Three of the four studies analyzing data from the osteoporosis GWAS data showed that inhibition of PCSK9 increased the risk of osteoporosis." (PMID 39010016, 2024). "Weighted median (P = 0.005) and weighted mode (P = 0.044) methods indicated a causal relationship was existing between PCSK9 inhibitors and osteoporosis." (PMID 38789568, 2024). "We chose these studies because they provided a large amount of representative data that helped to improve the statistical power of our analyses and allowed us to explore the association between PCSK9 and osteoporosis risk in different subgroups." (PMID 39010016, 2024). "The meta-analysis involving a total of 1,263,102 subjects, showed that PCSK9 inhibitors can increase osteoporosis risk (P < 0.05, I2, 39%)." (PMID 39010016, 2024). "In our study, we collected relevant GWAS pooled data for examining the causality between PCSK9 and osteoporosis by drug-targeted MR analysis." (PMID 39010016, 2024). "By integrating drug-targeted MR with mediation analysis, we aim to clarify the causal relationship between PCSK9 inhibitors and osteoporosis, offering valuable insights for clinicians in treatment decision-making." (PMID 38789568, 2024). "A causal relationship was found between LDL-C levels based on PCSK9 inhibitors and osteoporosis." (PMID 38789568, 2024). "However, the potential association between PCSK9 inhibitors and osteoporosis is unclear now." (PMID 38789568, 2024). "After identifying the impact of PCSK9 inhibitors on osteoporosis, we investigated the relationship between PCSK9 inhibitors and BMD levels in different age groups." (PMID 38789568, 2024). "PCSK9 inhibitors are now recommended for cardiovascular disease (CVD), but the impact of PCSK9 on osteoporosis remains uncertain." (PMID 39010016, 2024). "Mediation analysis indicated that 43.33% of the effect of PCSK9 inhibitors on osteoporosis was through BMD levels, while 56.67% was a direct effect." (PMID 38789568, 2024). "In individuals aged 45–60 years, PCSK9 inhibitors were observed to prevent osteoporosis by increasing BMD levels." (PMID 38789568, 2024). "Mediation analysis revealed that 43.33% of the impact of PCSK9 inhibitors on osteoporosis was mediated through BMD levels, with the remaining 56.67% being a direct effect." (PMID 38789568, 2024). "Subsequently, in a follow-up investigation, we adhered to the same criteria and observed that combining the IVW method with beta coefficients was beneficial in uncovering and exploring the relationship between PCSK9 inhibitors and osteoporosis." (PMID 38789568, 2024). "Through a “two sample MR” analysis on PCSK9 inhibitors and osteoporosis, 3 palindromic SNPs including rs12067569, rs11591147 and rs11583974 of the 13 IVs were removed." (PMID 38789568, 2024). "The indirect effect of PCSK9 inhibitors on osteoporosis through BMD accounted for 43.33%, while the direct effect accounted for 56.67%." (PMID 38789568, 2024). "Sensitivity analysis suggests horizontal pleiotropy exist in MR analysis between PCSK9 inhibitors and osteoporosis (finn-b-M13_OSTEOPOROSIS)." (PMID 39010016, 2024). "Although drugs targeting LDL-C are common in clinical practice, further research is needed to understand the impact of PCSK9 inhibitors on osteoporosis." (PMID 38789568, 2024). "The results of MR analyses examined by sensitivity analyses were incorporated into a meta-analysis for examining causality between PCSK9 and HMGCR inhibitors and osteoporosis." (PMID 39010016, 2024).
osteoporosis (continued). "Combining this approach with mediation analysis help we enhance our understanding of the effects of PCSK9 inhibitors on osteoporosis." (PMID 38789568, 2024). "To further explore the relationship between PCSK9 inhibitors and osteoporosis, we conducted drug-targeted MR analysis." (PMID 38789568, 2024). "IVW results indicated that while PCSK9 inhibitors helped decrease the occurrence of osteoporosis, the direct correlation was found to be weak." (PMID 38789568, 2024). "We found the risk of osteoporosis was reduced by 0.6% in those who used PCSK9 inhibitors compared with non-users (OR: 0.994, PIVW < 0.001)." (PMID 38789568, 2024). "Despite the observed increase in serum T25(OH)D levels following PCSK9 inhibitor administration, this study did not establish a causal relationship between serum T25(OH)D levels and osteoporosis." (PMID 38789568, 2024). "Hence, we employed Mendelian randomization (MR) analysis for examining PCSK9 inhibitor effects on osteoporosis." (PMID 39010016, 2024). "This suggested that osteoporosis was influenced by PCSK9 inhibitors." (PMID 38789568, 2024). "Whether PCSK9 inhibitors could elevate serum T25(OH)D levels and improve osteoporosis, was of big value for further clarifying." (PMID 38789568, 2024). "Such discoveries indicate that PCSK9 inhibitors may promote the development of osteoporosis by modulating estrogen levels." (PMID 39010016, 2024). "In addition, mediation analysis showed that PCSK9 inhibitors prevented osteoporosis by both direct effect and mediation effect." (PMID 38789568, 2024). "Thus PCSK9 ought to have an unforeseen function in osteoporosis." (PMID 39010016, 2024). "Therefore, we explored whether PCSK9 inhibitors were correlated with important factors related to osteoporosis." (PMID 38789568, 2024). "At the same time, we will also explore the relationship between different types of PCSK9 inhibitors and serum LDL-C levels, serum T25(OH)D levels, calcium supplements, and osteoporosis." (PMID 38789568, 2024). "However, contrary to our expectations that these SNPs failed to reduce the risk of osteoporosis and instead increased the chances of osteoporosis, these findings will help to achieve a deeper understanding of PCSK9’s effects and provide clues to the possible side effects of PCSK9." (PMID 39010016, 2024). "However, the link between PCSK9 and osteoporosis has not yet been thoroughly investigated." (PMID 39010016, 2024).
pulmonary hypertension (3 papers, 2023 to 2024). Increased pressure within the pulmonary circulation due to lung or heart disorder. "Additionally, higher levels of PCSK9 in BALF trigger pulmonary hypertension and cardiovascular complication." (PMID 39138259, 2024).
renal fibrosis (3 papers, 2022 to 2025). A final common manifestation of a wide variety of chronic kidney diseases characterized by glomerulosclerosis and tubulointerstitial fibrosis. "Mechanistically, PCSK9 inhibits fatty acid β-oxidation-related factors, and this altered metabolism affects renal fibrosis." (PMID 36552716, 2022).
sarcopenia (3 papers, 2021 to 2024). Progressive decline in muscle mass due to aging which results in decreased functional capacity of muscles. "This MR study suggested that PCSK9 is involved in sarcopenia pathogenesis and that its inhibition is associated with reduced ALM." (PMID 39254080, 2024). "To date, limited data exist on the risk of sarcopenia associated with the use of PCSK9 inhibitors, and further careful evaluation of the long‐term safety of PCSK9 inhibitors is warranted." (PMID 39254080, 2024). "Taken together, our findings indicate that if the function of PCSK9 plays a role in determining the risk of sarcopenia, it likely occurs through pathways other than the regulation of peripheral LDL." (PMID 39254080, 2024). "We performed a two‐sample Mendelian randomization (MR) study to investigate the causal association between the use of genetically proxied lipid‐lowering drugs (including statins, ezetimibe, and PCSK9 inhibitors, which use low‐density lipoprotein as a biomarker), and sarcopenia risk." (PMID 39254080, 2024). "Our results and existing evidence call for further caution in muscle-related adverse reactions of PCSK9 inhibitors that may increase the risk of sarcopenia." (PMID 38961447, 2024). "However, our MR findings indicated that genetically proxied inhibition of PCSK9 may actually increase the risk of sarcopenia, characterized by significantly reducing the muscle mass." (PMID 38961447, 2024). "In this study, we conducted comprehensive drug target MR analysis to evaluate the causal effects of the most commonly prescribed lipid-lowering drug classes including HMGCR, PCSK9, and NPC1L1 inhibitors on sarcopenia risk." (PMID 38961447, 2024). "Besides statins, the recent approval of PCSK9, and NPC1L1 inhibitors has led to a dearth of long-term adverse reaction data for risk of sarcopenia." (PMID 38961447, 2024). "Low ALM or LHGS are commonly observed in patients with these diseases, leading to reasonable speculation about the potential involvement of PCSK9 in the pathogenesis of sarcopenia." (PMID 39254080, 2024). "In this study, we aim to evaluate the causal impacts of the most commonly prescribed lipid-lowering drugs comprised of HMGCR, PCSK9, and NPC1L1 inhibitors on multiple sarcopenia-related traits via the MR approach and provide innovative recommendations for the clinical administration." (PMID 38961447, 2024). "In contrast, inhibition of PCSK9 may reduce appendicular lean mass (beta = -0.050, P = 1.40 × 10− 3), while inhibition of NPC1L1 showed no causal impact on sarcopenia-related traits." (PMID 38961447, 2024).
sickle cell disease (3 papers, 2020 to 2024). Sickle cell anemias are chronic hemolytic diseases that may induce three types of acute accidents: severe anemia, severe bacterial infections, and ischemic vasoocclusive accidents (VOA) caused by sickle-shaped red blood cells obstructing small blood vessels and capillaries. "This study focused on two therapeutically relevant genes, PCSK9 and BCL11A, which are targets for cholesterol reduction and treatment of β-thalassemia and sickle cell disease, respectively." (PMID 39275984, 2024).
tetanus (3 papers, 2021 to 2024). A serious infectious disorder that follows wound contamination by the Gram-positive bacterium Clostridium tetani. "Thus, a satisfactory safety profile of the peptide vaccine containing PCSK9 and tetanus epitopes was found." (PMID 38165521, 2024).
vasculitis (3 papers, 2021 to 2022). "In conclusion, our research showed for the first time that the anti-PCSK9 mAb1 (6 and 10 mg/kg) treatment attenuated the vasculitis via modulating the TLR2 and NF-ƙB pathway in HFD together with zymosan treated mice." (PMID 35911646, 2022). "The goal of the present study was to see whether anti-PCSK9 mAb1 might prevent vasculitis in C57BL/6 mice by blocking TLR2/NF-B activation in HFD and Zymosan-induced vasculitis." (PMID 35911646, 2022). "Therefore, the current investigation aimed to assess the effects of anti-PCSK9 mAb1 on vascular inflammation in HFD together with zymosan-induced vasculitis via inhibiting the TLR2 and NF-ƙB pathway." (PMID 35911646, 2022). "Further studies on PCSK9 showed that it played an important role in vasculitis." (PMID 35677050, 2022). "Current research tries to evaluate the role of anti-PCSK9 mAb1 in mitigating the HFD and Zymosan-induced vasculitis and its possible underneath mechanism." (PMID 35911646, 2022). "Anti-PCSK9 mAb1 has not yet been investigated for its role in HFD together with zymosan-induced vasculitis through regulation of the TLR2 and NF-ƙB pathway." (PMID 35911646, 2022).
vitamin D deficiency (3 papers, 2024 to 2025). A nutritional condition produced by a deficiency of VITAMIN D in the diet, insufficient production of vitamin D in the skin, inadequate absorption of vitamin D from the diet, or abnormal conversion of vitamin D to its bioactive metabolites. "Vitamin D levels were inversely correlated with insulin and HOMA-IR, and women with lower vitamin D levels exhibited higher PCSK9 concentrations, suggesting a potential link between vitamin D deficiency and metabolic dysregulation." (PMID 41516208, 2025). "Collectively, these results suggest that therapeutic strategies targeting PCSK9, correcting vitamin D deficiency, and promoting smoking cessation may provide clinically meaningful benefits for improving cardiometabolic and reproductive outcomes in women with PCOS." (PMID 41516208, 2025). "We hypothesized that serum PCSK9 concentrations are associated with lipid and glucose metabolism disturbances in women with PCOS, and that these associations may be modified by smoking and vitamin D deficiency." (PMID 41516208, 2025). "Overall, these findings indicate that PCSK9 regulation in PCOS may be driven predominantly by metabolic factors rather than PCOS status or smoking per se, and that metabolic status and vitamin D deficiency should be considered when assessing cardiometabolic risk in this population." (PMID 41516208, 2025). "Reintroduction after SAMS is challenging and may involve using alternate statins, intermittent dosing, correcting vitamin D deficiency, or transitioning to non-statin agents like ezetimibe or proprotein convertase subtilisin/kexin type 9 (PCSK9) inhibitors." (PMID 40688926, 2025).
acute monocytic leukemia (2 papers, 2025). Acute monoblastic leukemia (AML-M5), is one of the most common subtypes of acute myeloid leukemia (AML) that is either comprised of more than 80% of monoblasts (AML-M5a) or 30-80% monoblasts with (pro)monocytic differentiation (AML-M5b). "According to pre-clinical research, after silencing PCSK9 expression with siRNA, significant reduced IL-1α, IL-6, and TNF-α expression, as well as downregulated activation of the NF-κB pathway, were observed in human THP-1 (an acute monocytic leukemia cell line) cells." (PMID 40872487, 2025).
alcoholic cirrhosis (2 papers, 2021 to 2022). "Thus, our findings do not support an association of circulating PCSK9 and residual liver function at least in patients with alcoholic liver cirrhosis." (PMID 33461570, 2021). "PCSK9 protein levels were determined by ELISA in systemic vein (SVP), hepatic vein (HVP) and portal vein plasma of patients with mostly alcoholic liver cirrhosis." (PMID 33461570, 2021). "Associations of serum PCSK9 levels with circulating markers of liver function such as bilirubin, aminotransferases or the MELD score did not exist in patients with alcoholic cirrhosis." (PMID 35162992, 2022). "In alcoholic cirrhosis patients, plasma PCSK9 amounts did not correlate with C-reactive protein or IL-6 levels, which are commonly regarded as markers of systemic inflammation." (PMID 35162992, 2022).
allergic asthma (2 papers, 2024 to 2025). A asthma with a basis in a pathological type I hypersensitivity reaction. "Our findings support a potential causal relationship between PCSK9 activity and an increased risk of allergic asthma." (PMID 38623319, 2024). "Likewise, SMR analysis discovered an augmented expression of PCSK9 being linked with a heightened susceptibility to allergic asthma (OR = 1.21, 95% CI = 1.03–1.43; P = 0.02)." (PMID 38623319, 2024). "An experimental analysis found significant evidence for an association between PCSK9-mediated reduction in LDL cholesterol and reduced risk of allergic asthma." (PMID 40605076, 2025). "The IVW-MR analysis revealed significant evidence for an association between PCSK9-mediated LDL-C reduction and a decrease in the risk of allergic asthma (odds ratio [OR] = 1.31, 95% confidence interval [CI] = 1.11–1.56; P < 0.01)." (PMID 38623319, 2024). "PCSK9 inhibitors that reduce PCSK9 activity may be prioritized in future clinical trials investigating drugs for the prevention or treatment of allergic asthma." (PMID 40605076, 2025). "Thus, PCSK9 inhibitors, which reduce PCSK9 activity, might be considered a priority in future clinical trials investigating drugs for allergic asthma prevention or treatment." (PMID 38623319, 2024).